SMYD1 (SET and MYND domain containing 1)
Description:
Methylates histone H3 at 'Lys-4' (H3K4me), seems able to perform both mono-, di-, and trimethylation. Acts as a transcriptional repressor. Essential for cardiomyocyte differentiation and cardiac morphogenesis.
Synonyms: BOP; ZMYND22; KMT3D; ZMYND18
Tractability: No criterion of Open Targets' tractability assessment is met for any kind of drug.
Target class: Enzyme; Transferase
Gene: Protein-coding gene on chromosome 2 (88,067,773 to 88,113,384, forward strand). Ensembl gene ENSG00000115593.
Subcellular location: Cytoplasm; Nucleus
Pathways (Reactome):
Developmental Biology: Cardiogenesis
Gene Ontology:
Molecular function: protein binding; histone H3K4 methyltransferase activity; histone H3K4 trimethyltransferase activity; transcription corepressor activity
Biological process: positive regulation of myoblast differentiation; positive regulation of myotube differentiation; heart development; negative regulation of DNA-templated transcription; chromatin remodeling
Cellular component: nucleus; cytoplasm
Genetic constraint (gnomAD): Loss-of-function variants: 49 observed, 53.76 expected, observed/expected ratio (o/e) 0.91, 90% interval 0.72 to 1.16. The upper end of that interval is the gene's LOEUF score, 1.16, which puts it in group 5 of 6, group 1 being the genes least tolerant of losing a copy. Missense variants: 653 observed, 654.63 expected, observed/expected ratio (o/e) 1, 90% interval 0.94 to 1.06. Synonymous variants: 269 observed, 240.13 expected, observed/expected ratio (o/e) 1.12, 90% interval 1.01 to 1.24.
Homologues: Orthologues: chimpanzee SMYD1 (99% identical), macaque SMYD1 (99% identical), dog SMYD1 (96% identical), pig SMYD1 (96% identical), rabbit SMYD1 (96% identical), guinea pig SMYD1 (96% identical), rat Smyd1 (95% identical), mouse Smyd1 (94% identical), tropical clawed frog smyd1 (77% identical), zebrafish smyd1b (63% identical), zebrafish smyd1a (55% identical), Drosophila melanogaster Smyd3 (22% identical), and 8 more. Paralogues in human: SMYD2 (28% identical), SMYD3 (27% identical), SMYD4 (21% identical), SMYD5 (16% identical), ZMYND15 (13% identical).
Diseases named in the same sentence as SMYD1 in open-access papers:
SMYD1 is named in the same sentence as 38 diseases in open-access papers, as found by Europe PMC text mining. Sharing a sentence is not in itself a finding about the gene and the disease. The quoted sentences say what the papers report.
heart failure (9 papers, 2015 to 2026). Inability of the heart to pump blood at an adequate rate to meet tissue metabolic requirements. "Mutations in SMYD1 are known to cause cardiomyopathy and heart failure in humans, and loss of Smyd1 in mice results in a phenotype resembling AIC." (PMID 42102394, 2026). "In the adult myocardium, the loss of Smyd1 using inducible, cardiomyocyte-specific Smyd1 knockout mice leads to the massive downregulation of mitochondrial bioenergetics, cardiac hypertrophy, fibrosis and heart failure." (PMID 36980931, 2023). "Smyd1 was upregulated in a mouse model of hypertrophy and heart failure, and loss of function resulted in cellular hypertrophy and remodeling, ultimately leading to heart failure." (PMID 37504561, 2023). "Other studies examining muscle-specific chromatin regulators have indicated that SMYD1 is linked to the development of hypertrophic cardiomyocytes, leading to heart failure in mice." (PMID 36838987, 2023). "Overexpression of SMYD1 represses the transcription of genes, leading to the formation of ion channels in the heart, a process which causes heart failure." (PMID 36838987, 2023). "Originally, SMYD1 was reported to play a role in embryonic cardiac development, however, more recently SMYD1 has been shown to be differentially expressed in human heart failure patients and in mouse models of heart disease." (PMID 37212935, 2023). "We have previously shown that inducible cardiomyocyte-specific knockout of Smyd1 in mice leads to pathological organ remodeling, chamber dilation and heart failure." (PMID 37212935, 2023). "Knowing that SMYD1 plays a significant role in cardiac function, we became interested in evaluating SMYD1 expression levels in human heart failure patients." (PMID 37212935, 2023). "Another possibility in chromatin-bound Smyd1 is a transient phenomenon occurring early in the heart failure development, which is reverted in more mature stages of the disease." (PMID 32574189, 2020). "Perhaps a detailed parallel analysis of whole-cell and chromatin-bound Smyd1 during different time points of pressure overload-induced heart failure develppment should be performed in a future study." (PMID 32574189, 2020). "This correlation suggests SMYD1 contributes to heart failure likely through affecting ion homeostasis of failing hearts." (PMID 27790639, 2016). "Variants in human Smyd1 are associated with cardiomyopathies and cardiac failure, which suggests Smyd1 is a critical factor required for normal heart development and function." (PMID 39858599, 2025). "However, the overall signaling vector from Smyd1 and Perm1 during evolving heart failure appears to be highly complex and needs further calrification." (PMID 32574189, 2020). "It remains to be demonstrated whether the release of Smyd1 from the Perm1 promoter is a necessary or sufficient factor of Perm1 downregualtion in heart failure." (PMID 32574189, 2020). "These together suggest a new possibility that SMYD1 could be involved in heart failure through inflammation and regulating cytotoxic T-cell function and INFγ signaling pathways." (PMID 27790639, 2016). "Further analysis of Smyd1 function in adult tissues could lead to a better understanding of these mechanisms and allow development of novel and effective therapeutic strategies against heart failure." (PMID 25803368, 2015). "In addition, Smyd1 interacts with HDAC via the deacetylase inhibitor TSA, which leads to decreased expression of ANF, a cardiac natriuretic peptide and established marker for heart failure." (PMID 37504561, 2023).
cardiomyopathy (7 papers, 2015 to 2026). A disease of the heart muscle or myocardium proper. "While SMYD1 has been the subject of several studies in zebrafish and mice, since it was first identified, only in the last few years have human patients been identified with variants in the SMYD1 gene exhibiting cardiomyopathies." (PMID 36980931, 2023). "Tg(myl7:Lifeact-GFP) transgenic zebrafish could be a useful model for future studies of cardiomyopathy from Smyd1 deficiency." (PMID 34765602, 2021). "SMYD1 is expressed in the heart and skeletal muscle in both mouse and zebrafish; knockdown in mice leads to a fatal cardiomyopathy while a knockdown of smyd1b in zebrafish leads to a dual-skeletal and cardiomyopathy that is lethal at 7 days past fertilization." (PMID 26544721, 2015). "Finally, decreased abundance of SMYD1, EDF1 and PDLI5 might provide molecular insights into the nature of the dilatative cardiomyopathy described in this mouse model." (PMID 30153853, 2018).
hypertrophic cardiomyopathy (4 papers, 2016 to 2023). A condition in which the myocardium is hypertrophied without an obvious cause. "Genetic mutations in human SMYD1 are associated with congenital and hypertrophic cardiomyopathies in human." (PMID 34765602, 2021). "Recent studies demonstrated that genetic mutations in human SMYD1 are associated with dilated cardiomyopathy and hypertrophic cardiomyopathy." (PMID 34765602, 2021). "No clinical cases of congenital heart defects arising from SMYD1 mutations have been reported, but one report found single-nucleotide polymorphisms in exon 6 associated with hypertrophic cardiomyopathy." (PMID 26935107, 2016). "The first patient is a female proband exhibiting hypertrophic cardiomyopathy (HCM) and biventricular heart failure carrying a truncating homozygous MYBPC3 variant c.1224-52G>A (IVS13-52G>A) and a novel homozygous variant (c.302A>G; p.Asn101Ser) in the SMYD1 gene." (PMID 36980931, 2023).
breast carcinoma (3 papers, 2023 to 2026). "Conversely, in breast cancer, SMYD1 expression is lower than that of other SMYD family members, and Kaplan‒Meier curve analysis indicates that lower SMYD1 expression is correlated with poor prognosis." (PMID 39482529, 2024).
cardiac hypertrophy (2 papers, 2023). "SMYD1, a striated muscle-specific lysine methyltransferase, was originally shown to play a key role in embryonic cardiac development but more recently we demonstrated that loss of Smyd1 in the murine adult heart leads to cardiac hypertrophy and failure." (PMID 37212935, 2023).
B-cell non-Hodgkin lymphoma (1 paper, 2017). The most common type of non-Hodgkin lymphoma. "Smyd1 has been reported to regulate endothelial cells and skeletal muscle and to be mutated in an indolent B cell non-Hodgkin lymphoma but not in brain tumors or in cerebellar development." (PMID 29029386, 2017).
colorectal adenocarcinoma (1 paper, 2024). The most common type of colorectal carcinoma. "In the case of SMYD1, the majority of alterations were observed as low-level gains in colorectal adenocarcinoma (18.5%), stomach adenocarcinoma (16.1%), lung squamous cell carcinoma (43.1%), lung adenocarcinoma (20%), endometrial carcinoma (17.1%), and uterine carcinosarcoma (46.4%)." (PMID 38892284, 2024).
colorectal cancer (1 paper, 2024). A primary or metastatic malignant neoplasm that affects the colon or rectum. "Specifically, SMYD5 exhibited a mutation frequency of 2.3% in colorectal cancer, while SMYD1 demonstrated a mutation frequency of 2.3% in both lung adenocarcinoma and lung squamous cell carcinoma." (PMID 38892284, 2024).
congenital heart disease (1 paper, 2025). A heart disease that is present at birth. "The mis-regulation or absence of these transcription factors are also associated with congenital heart disease, which broadens the effect and severity Smyd1 has on vertebrate heart development." (PMID 39858599, 2025).
congenital myopathy (1 paper, 2016). "The phenotype observed in the Smyd1 CKO is most similar to a subset of clinical CNM categorized as ‘congenital myopathy with prominent nuclear internalization and large areas of myofibrillar disorganization’." (PMID 26935107, 2016). "Despite its important functions in striated muscle, SMYD1 mutations have not been identified in any patient with congenital myopathy." (PMID 26935107, 2016).
dilated cardiomyopathy (1 paper, 2021). Cardiomyopathy which is characterized by dilation and contractile dysfunction of the left and right ventricles. "An infant patient carrying a SMYD1 mutation suffered from dilated cardiomyopathy and needed heart transplantation at the infant stage." (PMID 34765602, 2021).
endometrial carcinoma (1 paper, 2024). A malignant tumor arising from the epithelium that lines the cavity of the uterine body. "In endometrial carcinoma, the mutation frequencies were 3.3% for SMYD1, 2.1% for SMYD2, 2.1% for SMYD3, 2.1% for SMYD4, and 2.4% for SMYD5." (PMID 38892284, 2024).
gastric cancer (1 paper, 2024). A primary or metastatic malignant neoplasm involving the stomach. "Additionally, in gastric cancer, high expression of ankyrin repeat and SOCS box-containing 5 (ASB5), secreted frizzled-related protein 1 (SFRP1), SMYD1, and tachykinin receptor 2 (TACR2) is associated with short survival times and high risk in these patients." (PMID 39482529, 2024).
muscular dystrophy (1 paper, 2016). Muscular dystrophy (MD) refers to a group of more than 30 genetic diseases characterized by progressive weakness and degeneration of the skeletal muscles that control movement. "Thus, sarcolemmal integrity is intact in Smyd1 CKO myofibers, which is indicative of myopathy rather than muscular dystrophy." (PMID 26935107, 2016).
myopia (1 paper, 2024). "Because the retina is a neural tissue, the expression of numerous genes linked to cardiac muscle (MYBPC3, ACTC1, MYL3, MYH7, MYH7B) or to skeletal muscle (MYL1, SMYD1, TNNI2, MYH1B, ACTA1, TNNT3) presents a conundrum for explaining a mechanism for myopia progression." (PMID 39028695, 2024).
prostate carcinoma (1 paper, 2023). A carcinoma that arises from epithelial cells of the prostate gland. "Only the SMYD1 gene had prognostic properties and also seemed to play a role in the pathogenesis of prostate cancer in addition to its role in cardiac function." (PMID 36838987, 2023).
splenic marginal zone lymphoma (1 paper, 2021). Splenic marginal zone lymphoma is a rare, indolent B-cell non-Hodgkin lymphoma characterized by abnormal clonal proliferation of mature B-lymphocytes with involvement in the spleen, bone marrow and, frequently, the blood. "For example, SMYD1 mutations have been implicated in splenic marginal zone lymphoma (SMZL)." (PMID 34335697, 2021).
tibial muscular dystrophy (1 paper, 2024). A distal myopathy characterized by weakness of the muscles of the anterior compartment of lower limbs, appearing in the fourth to seventh decade of life. "In addition, TTN is a gene encoding the giant skeletal muscle protein Titin, which is of great value in the study of tibial muscular dystrophy (TMD); while SMYD1 (the protein 1 gene of the SET and MYND domains) has an important role in sarcomere tissue." (PMID 39096856, 2024).
uterine carcinosarcoma (1 paper, 2024). A usually aggressive malignant neoplasm arising from the uterine corpus and less often the cervix. "Moreover, in uterine carcinosarcoma, the mutation frequencies were 5.1% for SMYD1 and 2.5% for SMYD4." (PMID 38892284, 2024).
cancer (7 papers, 2006 to 2024). A tumor composed of atypical neoplastic, often pleomorphic cells that invade other tissues. "The human hepatoma-derived growth factor (HDGF), containing the chromatin-associated N-terminal PWWP domain capable of binding the SMYD1 promoter, participates in various cellular processes and is involved in human cancers." (PMID 29321480, 2018). "COSMIC database contains 170 unique cancer samples with SMYD1 mutations out of 24,615 total samples." (PMID 26498442, 2015). "Members of this family are direct regulators of cancer (Smyd3) and essential developmental processes (Smyd1)." (PMID 16805913, 2006). "Extensive studies on the functional role of SMYD1 in cancer have not been conducted, but research on its role as a prognostic marker of various cancer types is ongoing." (PMID 39482529, 2024). "We identified one gene, SMYD1, with recurrent somatic mutations in our collection of SMZL, which has not been specifically associated to cancer in the past." (PMID 26498442, 2015).
tumor (5 papers, 2015 to 2023). "Moreover, the position in the 3’ UTR of SMYD1, where we found one of the mutations, is a predicted target of miR28, a recently described potent tumor suppressor in B-cell lymphomagenesis." (PMID 26498442, 2015). "SMYD2 is widely distributed across normal and tumor tissues and, like SMYD1, is involved in cardiac and skeletal muscle cell differentiation and maturation." (PMID 36816359, 2023). "Survival analysis showed that SMYD1 was significantly correlated with RFS in ESCA patients, and with OS and RFS in STAD patients, suggesting that SMYD1 may be a potential tumor marker in these patients." (PMID 34335697, 2021). "Similarly, mice bearing mouse G3 MB tumor cells over-expressing Smyd1 or Ubn2 survived with similar latency compared to tumor cells transduced with empty vector (upper right and lower left)." (PMID 29029386, 2017). "There were four non-silent mutations in this tumor, all missense SNVs: Lrfn2 R656H, Smyd1 R237Q, Ubn2 Q549K and Wdr11 I46T." (PMID 29029386, 2017). "We identified mutations that seem to be heterozygous and clonal as they show allele frequencies of >40 % in the WES and 46–53 % in the validation experiments (NOTCH2, SMYD1, MYD88), with the proximity to 50 % providing an indirect evidence for high tumor cell purity." (PMID 26498442, 2015). "Indeed, enforced expression of wild-type WDR11 (but not LRFN2, Ubn2, Smyd1) hindered G3 MB development, which is in-line with our hypothesis about its tumor suppressor activity." (PMID 29029386, 2017).
heart disease (3 papers, 2021 to 2023). "Our study, in addition to the emerging role in heart disease, suggests that Smyd1 may be of therapeutic interest." (PMID 34944023, 2021).
myopathy (2 papers, 2016 to 2023). A disease of the muscle in which the muscle fibers do not function properly. "Because Smyd1 heterozygous mice are phenotypically normal, myopathies due to Smyd1 mutations would likely be autosomal recessive." (PMID 26935107, 2016). "Specific inactivation of Smyd1 in skeletal myocytes resulted in a myopathy with excessive internal nuclei, atrophy and myofibril disarray." (PMID 26935107, 2016). "In summary, elimination of SMYD1 from skeletal muscle produces a myopathy characterized by increased internal nuclei, hypotrophy, myofibrillar disarray and weakness." (PMID 26935107, 2016). "Suspecting some form of myopathy in Smyd1 CKO mice, we performed several experiments to assay strength." (PMID 26935107, 2016). "In addition, the inactivation of SMYD1 in skeletal muscle results in myopathy characterized by myofiber hypotrophy and myofibrillar disorganization/breakdown." (PMID 38201213, 2023). "Thus, human SMYD1 loss-of-function mutations might be so detrimental to heart development that, like for mice, embryonic survival is compromised and myopathy is not assessed." (PMID 26935107, 2016).
neurodegenerative disease (2 papers, 2022 to 2023). A disorder of the central nervous system characterized by gradual and progressive loss of neural tissue and neurologic function. "Recent work suggests that Smyd1 functions also in neuronal cells as regulators of genes disrupted in different neurodegenerative diseases." (PMID 36436561, 2022). "The SMYD1 gene belongs to a family of SMYD proteins related to immunity and inflammatory control and has been involved in neurodegenerative diseases." (PMID 36846236, 2023).
SMYD1 also shares sentences with these, for which no sentence is quoted: myocardial infarction (2 papers); brain tumors (1); colon cancer (1); Emery-Dreifuss muscular dystrophy (1); esophageal squamous cell carcinoma (1); ischemic cardiomyopathy (1); lung adenocarcinoma (1); lung carcinoma (1); lung squamous cell carcinoma (1); Myocardial fibrosis (1); myocardial ischemia (1); pancreatic cancer (1); stomach adenocarcinoma (1); uterine tumors (1).